HIF1A (hypoxia inducible factor 1 subunit alpha)
Diseases named in the same sentence as HIF1A in open-access papers (continued):
Sharing a sentence is not in itself a finding about the gene and the disease.
Hyperglycemia (continued). "It has been proven that autophagy dysfunction accelerates kidney senescence in a hyperglycemia state, while upregulated HIF-1α has been proven to unblock the autophagy-lysosome pathway." (PMID 38720731, 2024). "HIF1A, which expresses many hypoxia-induced genes, is also upregulated by hyperglycemia and consequently induces VEGF and HMOX1, thereby promoting angiogenesis and tumor growth." (PMID 38200154, 2024). "Studies have shown that the basic status of the microvasculature is one of low O2 and low metabolism, although the role of HIF-1α in the tissue response to hyperglycemia and hypoxia appears to be rather variable." (PMID 36982254, 2023). "HIF-1α plays an unpredictable role in the response of the tissue to hyperglycemia, and current data suggest that it is probably better to activate the CO2 hypoxemic response than the HIF-1α hypoxic pathway." (PMID 36982254, 2023). "Hyperglycemia decreases angiogenesis in endothelial cells, and it affects the stability of hypoxia-inducible factor 1-alpha (HIF-1a) to target genes such as the vascular endothelial growth factor (VEGF) to promote wound healing and tissue repair." (PMID 37446104, 2023). "Concisely, hyperglycemia seems to inhibit HIF-1α expression induced by low-oxygen conditions, suggesting a weaker HIF-1α-dependent response to hypoxia in DM." (PMID 37305566, 2023). "In E10.5 mouse embryos exposed to maternal hyperglycemia, the level of Hif1α protein was upregulated, and 20 out of 22 Hif1α-responsive genes were upregulated, including enzymes regulating glucose metabolism, such as Glut1." (PMID 38003449, 2023). "Hyperglycemia has been shown to reduce HIF-1α expression in human microvascular endothelial cells and rat proximal tubule cells." (PMID 37048134, 2023). "The same experiment also found that HIF-1α levels were similarly affected by the induction of hyperglycemia via STZ." (PMID 37637673, 2023). "Cobalt has been proposed as a treatment for type II diabetes since it promotes the production of HIF1-α which is suppressed by hyperglycemia." (PMID 37367855, 2023). "Nevertheless, the majority of in vitro studies have concluded that hyperglycaemia is responsible for reduced HIF-1α stability and compromised transcriptional activation function via impaired interaction with the transcriptional coactivator p300." (PMID 37686781, 2023). "We showed that HIF1A expression, its protein’s localization and transactivation function didn’t change in response to hyperglycemia in the control normal cell line, despite the reduction of WWOX protein." (PMID 35328751, 2022). "For example, it has been described that hyperglycemia destabilizes HIF-1α and impairs its function at a concentration of 30 mM." (PMID 35395929, 2022). "Even with the preserved sensitivity of HIF-1α Pro582Ser to the hyperglycemia-induced HIF-1α destabilization, the transactivation activity of this SNP is increased." (PMID 35969320, 2022). "The HIF-1α in diabetic patients with HIF-1α rs11549465 SNP is resistant to hyperglycemia-induced inhibition of HIF-1α activity and therefore this SNP has a protective role against the progression of PDR among diabetic patients." (PMID 35969320, 2022). "This means that LW6 can reduce radiation tolerance of rectal cancer in hyperglycemia by reducing HIF-1α level." (PMID 36011045, 2022). "To further study the mechanism by which Set7_1a prevents HIF-1α degradation, we performed immunoprecipitation with an anti-methyl lysine antibody in hyperglycemia-induced HUVECs treated with Set7_1a for 12 h under hypoxia." (PMID 35859119, 2022). "The results suggested that hyperglycemia resulted in a higher level of expression of HIF-1α than in euglycemic conditions." (PMID 36011045, 2022). "Otherwise, inhibition of HIF-1α decreased mitophagy induced by hyperglycemia and aggravated mitochondrial dysfunction." (PMID 36017378, 2022).
Hyperglycemia (continued). "First, we demonstrated that hyperglycemia decreased the levels of HIF-1α under both hypoxic and normoxic conditions in HUVECs without affecting the level of SET7/9." (PMID 35859119, 2022). "We found that patients with hyperglycemia rectal cancer have a poor prognosis which positively correlates with HIF-1α expression." (PMID 36011045, 2022). "In contrast, hyperglycaemia has been shown to decrease the stabilisation of HIF-1α and reduce the expression of hypoxia responsive element (HRE) genes associated with bone regeneration." (PMID 35977987, 2022). "Overall, HIF-1α inhibitors were able to block the hyperglycemia-induced GLUT1-OGT-HIF-1α signaling pathway and reduce rectal cancer chemoradiation resistance." (PMID 36011045, 2022). "Even more important, recent experimental evidence indicates that hyperglycemia sensitizes kidneys to hypoxia-induced fibrosis via HIF-1α upregulation." (PMID 36358555, 2022). "WWOX downregulation resulted in HIF1α increase in normoxia normoglycemia and hyperglycemia condition (both p < 0.01)." (PMID 35328751, 2022). "Hyperglycaemia decreased HIF-1α stabilisation and VEGF expression in response to hypoxia after 1 day (P ≤ 0.05)." (PMID 35977987, 2022). "In hyperglycaemia conditions, the HIF-1α mimetics (CoCl2 and DMOG) increased bone nodule size (percentage of surface area with nodules above 30 μm) and area compared to untreated controls with similar level of glucose." (PMID 35977987, 2022). "Hyperglycaemia also induces the accumulation of methylglyoxal, which mediates HIF-1α destabilisation in a PHD- or VHL-independent manner." (PMID 33496820, 2021). "In our experiments, hyperglycemia enhanced the expression of HIF-1α and the tested samples helped increase it even more, therefore leading to protection against the detrimental effects of hypoxia." (PMID 34961280, 2021). "Many studies have aimed to elucidate the relationship between HIF-1a gene expression in cells and hyperglycemia." (PMID 34394393, 2021). "Inhibition of JAK2 and HIF1A expression can partially attenuate hyperglycaemia-elicited oxidative stress." (PMID 34956587, 2021). "Previous studies have shown that hyperglycemia destabilizes HIF-1α and impairs its function in diabetic mice through a VHL-dependent mechanism." (PMID 34099651, 2021). "The activity of HIF-1 is mainly determined by HIF-1a, which is regulated by hypoxia and hyperglycemia." (PMID 34394393, 2021). "Their biological effects were tested on HUVECs exposed to normoglycemia and hyperglycemia and showed a significant reduction of oxidative stress and of the γH2AX formation and significantly improved the expression of the HIF1-α." (PMID 34961280, 2021). "Three interrelated candidate mechanisms are ER stress and hyperglycemia, both known to induce mitochondrial ROS production, and stabilization of Hif‐1α in response to superoxide/hydrogen peroxide produced from site IIIQo." (PMID 34521156, 2021). "Taken together, these results exhibit a new mechanism by which HIF-1α protects against hyperglycemia-induced oxidative injury and enhances mitophagic activity, at least partially via Parkin/PINK1 signaling pathway in tubular cells." (PMID 35186974, 2021). "The polyphenolic-enriched extracts proved a significant reduction of oxidative stress and γ-H2AX formation and improved the expression of HIF-1α, suggesting their protective role on endothelial cells in hyperglycemia." (PMID 34961280, 2021). "In cells exposed to hyperglycemia, HIF1-α expression enhanced significantly (p < 0.01), this behavior being amplified by the association of the two extracts (p < 0.001, p < 0.01)." (PMID 34961280, 2021). "Hyperglycemia augments oxidative stress and contributes to the overproduction of ROS, which, in turn, downregulates HIF-1a levels via multiple possible mechanisms." (PMID 34394393, 2021).
Hyperglycemia (continued). "Hyperglycemia-induced inhibition of NER by destabilization of HIF-1α can be considered a potential mechanism to promote genomic instability and increase cancer susceptibility in people with T2D." (PMID 34426491, 2021). "The link between all these parameters in hyperglycemia is represented by the oxidative stress, which activates transcription factors including NF-κB and HIF-1α and induces DNA lesions." (PMID 34961280, 2021). "Hyperglycemia negatively regulates HIF-1α stability and its nuclear translocation by upregulation of prolyl hydroxylase domain protein 2 (PHD2) and PHD3." (PMID 33546224, 2021). "These two extracts proved a significant antioxidant activity, inhibited the γ-H2AX formation, and improved the expression of HIF1-α, suggesting their protective role on endothelial cells exposed to hyperglycemia." (PMID 34961280, 2021). "Hyperglycemia can mediate diabetic nephropathy by inducing an increase in HIF-1α expression and regulating the expression of downstream GLUT130." (PMID 34759325, 2021). "We conducted gene expression analysis and molecular mechanistic studies in human umbilical vein endothelial cells (HUVECs) induced by hyperglycemia and hypoxia using RNA sequencing (RNA-seq) and small interfering HIF-1α (si-HIF-1α)." (PMID 34479471, 2021). "HIF-1α downregulation reduced acute hyperglycemia-induced cerebral hemorrhage transformation in the ischemic hemisphere and decrease BBB injury induced by rat neonatal stroke." (PMID 34434231, 2021). "The effect of hyperglycemia on HIF1-α level was further investigated and it was found that glucose affected HIF1 expression only under hypoxic conditions in human dermal fibroblasts (HDF)." (PMID 34225729, 2021). "The results showed that hyperglycemia induced oxidative stress and the activation of NF-kB, increased the expression of HIF1-α, and triggered DNA lesions." (PMID 34961280, 2021). "Their effects on hyperglycemia were evaluated by the quantification of oxidative stress and NF-ĸB, pNF-ĸB, HIF-1α, and γ-H2AX expressions." (PMID 34961280, 2021). "There are multiple pathogenic factors explaining this delayed wound healing, including hyperglycemia, hypoxia, impaired HIF-1α activity, and the impaired expression and activities of the cytokines and growth factors required for normal healing process." (PMID 34356303, 2021). "Hyperglycemia in T2D has been reported to significantly reduce levels of HIF-1α; however, the effect of elevated glucose on HIF-1α regulation of NER has not been described." (PMID 34426491, 2021). "Hyperglycaemia inhibits the activity of both N-terminal and C-terminal transactivation domains of HIF-1α." (PMID 33496820, 2021). "Hyperglycaemia not only inhibits HIF-1α stability, but also represses the transactivation activity of HIF-1." (PMID 33496820, 2021). "Hyperglycemia induces an accumulation of hypoxia-inducible factor-1 alpha (HIF-1α) that mediates the increase in both glucose breakdown through the anaerobic pathway and the activity of cellular lactate dehydrogenase (LDH)." (PMID 34449579, 2021). "Studies have shown that hyperglycemia can significantly upregulate the expression of HIF-1α and its target gene VEGF in the brain microvasculature after MCAO; this further aggravates BBB disruption after ischemic brain injury." (PMID 34966392, 2021). "Exposure to hyperglycemia induced oxidative stress and the activation of NF-ĸ increased the expression of HIF-1α and produced DNA lesions." (PMID 34961280, 2021). "This pathway is compromised in diabetic patients, as hyperglycemia is known to reduce SDF1 expression through inactivation of its transcriptional regulator hypoxia-inducible factor-1 alpha (HIF-1α)." (PMID 32718071, 2020). "Experiments on cells cultured under hyperglycemia and hypoxia have shown increased degradation of HIF-1α protein, consistent with the results of this study." (PMID 33692685, 2020).
Hyperglycemia (continued). "The stabilization of HIF-1α is regulated by oxygen-dependent prolyl hydroxylation of proline domains located in Pro402 and Pro564, which is significant for the effect of hyperglycemia on HIF-1α." (PMID 32658866, 2020). "Hypoxia-inducible factor-1-alpha (HIF-1α), a major regulator of VEGF transcription, has been shown to be closely associated with hyperglycaemia and insulin secretion." (PMID 32528282, 2020). "Previous studies have shown that sevoflurane post-conditioning (SPostC) exerts a protective effect against myocardial ischemia/reperfusion injury by HIF-1α, but the protective effect is weakened or even disappeared under hyperglycemia." (PMID 33692685, 2020). "When podocytes were exposed to glucose for up to 6 days, the cellular expression level of HIF-1α increased in a temporal manner, indicative of hyperglycemia-induced podocyte hypoxia." (PMID 33202982, 2020). "This impairment in vascularization can result from hyperglycemia-induced inhibition of HIF-1α, which is transcription factor regulating the expression of vascular endothelial growth factor (VEGF)." (PMID 33013447, 2020). "Clinical and experimental studies indicate that hyperglycemia suggests a state of pseudohypoxia and activates HIF-1α activity for adaptation of hypoxia." (PMID 32658866, 2020). "We found that HIF-1α Pro402Ala/Pro564Ala/Pro582Ser has the same stability as HIF-1α Pro402Ala/Pro564Ala and that it is still sensitive to the hyperglycemia-dependent destabilization of HIF-1α in hypoxia." (PMID 31214621, 2019). "Further studies suggested that hyperglycemia disrupts the interaction of HIF-1α with Hsp90, a known cause of proteasomal degradation of HIF-1α." (PMID 31676796, 2019). "Here, we assessed the roles of miR‐125b‐5p and miR‐146a‐5p in HIF‐1α/SP1‐mediated ROBO4 expression in vivo in diabetic rats or in vitro in RPE cells under hyperglycaemia or hypoxia." (PMID 31094072, 2019). "Both studies reported that thioredoxin administration was able to overcome hyperglycemia-induced HIF-1α reduction and upregulated HIF-1α levels, which eventually enhanced wound healing by increasing blood supply to the wound site." (PMID 30654793, 2019). "The suppressive effects of specific siRNAs on hyperglycaemia‐induced HIF‐1α, SP1, and ROBO4 up‐regulation were also observed by Western blotting." (PMID 31094072, 2019). "Here we studied the mechanism and consequences of impaired HIF-1α regulation in human proximal tubular HK-2 cells incubated in hyperglycemia." (PMID 31676796, 2019). "HIF-1α mRNA levels at 1 and 3 h of CoCl2 were unchanged under euglycemia-CoCl2 and hyperglycemia-CoCl2." (PMID 29351188, 2018). "Both hyperglycemia and metformin induced changes in the expression of genes involved in the O-GlcNAcylation status and HIF1A pathway." (PMID 30217067, 2018). "Experiments with cells cultured in an environment combining hyperglycemia and hypoxia show increased degradation of the HIF-1α protein." (PMID 30158902, 2018). "Since the combination of hypoxia and hyperglycemia increases degradation of the HIF-1α protein, the ability of the diabetic heart to respond to hypoxic conditions is compromised." (PMID 30158902, 2018). "We examined the role of HIF-1α in the early stage of disease using the STZ-induced diabetic mouse model characterized by hyperglycemia (blood glucose levels > 13.9 mmol/L) and insulinopenia." (PMID 28774305, 2017). "Both Wt and Hif1α+/− mice developed high levels of hyperglycemia after STZ injections over the 6-week study." (PMID 28774305, 2017). "Chrysin deterred hyperglycemia-elicited induction of the pro-angiogenic proteins of HIF-1α and VEGF involved in retinal neovascularization." (PMID 27918469, 2016). "Regulation of VEGF expression is complex, and HIF-1α is one of the transcription factors that regulate VEGF expression under hyperglycemia." (PMID 27649243, 2016). "Further investigation into HIF-1α stabilization would be suggest as a possible upstream mechanism of PRC2 induction in hyperglycemia." (PMID 25884496, 2015).
Hyperglycemia (continued). "Hyperglycemia regulates HIF-1α protein stability and functions, destabilizing it, ultimately resulting in poor cell and tissue responses to hypoxia." (PMID 24564828, 2014). "Exercise reduced urinary levels of albumin and also maintained the number of podocytes in the exercised KK-Ay mice independently of improvements of overweight and hyperglycemia, although moderate-intensity exercise increased expression of HIF-1α." (PMID 22899901, 2012). "In mice on a high sucrose diet (40% of the diet composition vs 15% in our study), HIF-1α knockout in the liver increased fasting hyperglycemia and glucose intolerance due to impaired utilization of excessive dietary carbohydrates." (PMID 23049707, 2012). "The results reported in this paper are consistent with a number of sparse results and provide a rationale for observations such as that hyperglycemia inhibits hypoxia-induced stabilization of HIF-1α." (PMID 21124777, 2010). "Recently hyperglycemia has been demonstrated to inhibit HIF-1α expression, inhibit hypoxia-induced decreased proliferation of vascular smooth muscle cells and a concomitant decrease in hypoxia response element (HRE) promoter transactivation." (PMID 18447926, 2008). "A similar effect of hyperglycemia on reduction of Hif-1α levels and apoptosis has been demonstrated in vascular smooth muscle cells." (PMID 18447926, 2008). "Hypoxia-inducible factor-1 alpha (HIF-1α) is crucial for adaptation to hypoxic conditions; yet, its sustained activation in COPD has been associated with elevated hepatic gluconeogenesis and exacerbated hyperglycemia." (PMID 40142617, 2025). "Hyperglycemia destabilizes HIF-1α expression through VHL-dependent and MGO-mediated mechanisms." (PMID 41155932, 2025). "In DKD, hyperglycemia (HG) creates not only a HOX milieu but also represses Hif1α signaling." (PMID 40739162, 2025). "Hyperglycemia induces oxidative stress, compromising mitochondria energy metabolism disturbances, leading to cardiomyocyte hypoxia and dysregulation of hypoxia-inducible factor-1α (HIF-1α), thereby exacerbating diabetic myocardial injury." (PMID 39920720, 2025). "In addition, hyperglycemia and enhanced glycolysis can activate HIF-1α and the production of mitochondrial reactive oxygen species to increase the replication of novel coronavirus in human monocytes." (PMID 39886017, 2025). "However, the activity is submaximal to the level of hypoxia that is observed in DKD, since HIF-1α expression is, to some extent, impaired by hyperglycemia." (PMID 39648258, 2025). "Additionally, hyperglycemia and high ROS levels inhibit HIF-1α activity; however, these mechanisms require further validation." (PMID 41155932, 2025). "Thus, the effects of metformin on HIF-1α in the diabetic testis appear context-dependent, aiming to restore physiological hypoxic adaptation while suppressing hyperglycemia-induced maladaptive activation." (PMID 40867634, 2025). "The TBK1 inhibitor reverses hyperglycemia-induced HIF-1α expression." (PMID 38674050, 2024). "Moreover, the use of an iron chelator, deferoxamine was shown to correct the impairment of HIF-1α/p300 binding induced by hyperglycemia and normalize the transactivation of HIF-1α." (PMID 38790642, 2024). "Hyperglycemia disrupts HIF-1α stability and this disruption may be mediated by PHD or VHL, PHD inhibition or VHL inactivation can largely rescue HIF-1α stability, but the underlying mechanism is not fully understood." (PMID 37251664, 2023). "Furthermore, the hyperglycemia-induced degradation of HIF-1α contributes to the impaired response of cardiomyocytes to hypoxia." (PMID 37048134, 2023). "Taking advantage of the findings showing that hyperglycemia increases HIF-1α gene transcription and induces the HIF-1 transcriptional activity irrespective of the oxygen levels, in an in vitro study, it was shown that high glucose (HG) condition promotes the degradation of HIPK2." (PMID 37345014, 2023).